IL6 (interleukin 6)
Diseases named in the same sentence as IL6 in open-access papers (continued):
Sharing a sentence is not in itself a finding about the gene and the disease.
Strabismus (1 paper, 2021). A misalignment of the eyes so that the visual axes deviate from bifoveal fixation. "We found the expression of INF-γ, IL-10, IL-12p70, and IL-17A in tears of strabismus patients, which were no significantly higher than those of normal subjects, while IL-6 and TNF-α were statistically significant." (PMID 34659636, 2021).
Subdural Effusion (1 paper, 2025). Leakage and accumulation of CEREBROSPINAL FLUID in the subdural space which may be associated with an infectious process; CRANIOCEREBRAL TRAUMA; BRAIN NEOPLASMS; INTRACRANIAL HYPOTENSION; and other conditions. "High CRP and Escherichia coli in blood bacterial culture were risk factors for subdural effusion that may be associated with blood–brain barrier function impairment caused by interleukin 6 or nitric oxide." (PMID 39974751, 2025).
sudden sensorineural hearing loss (1 paper, 2023). Sensorineural hearing loss which develops suddenly over a period of hours or a few days. "Changes in the serum levels of cytokines, such as tumor necrosis factor-α (TNF-α) and interleukin-6 (IL-6), have been related with poor prognosis in patients with sudden sensorineural hearing loss." (PMID 37733709, 2023).
Superior Vena Cava Syndrome (1 paper, 2026). A condition that occurs when the obstruction of the thin-walled SUPERIOR VENA CAVA interrupts blood flow from the head, upper extremities, and thorax to the RIGHT ATRIUM. "This case highlights the importance of early recognition and multidisciplinary management of superior vena cava syndrome in pregnancy and raises the hypothesis that pregnancy-associated immunologic changes, including interleukin-6-mediated pathways, may contribute to accelerated disease progression." (PMID 42136874, 2026).
T-cell acute lymphoblastic leukemia (1 paper, 2024). Acute lymphoblastic leukemia of T-cell origin. "We recently reported that in a transgenic murine model of Notch3-dependent T-cell acute lymphoblastic leukemia there is an accumulation of myeloid-derived suppressor cells, dependent on both Notch signaling deregulation and IL-6 production inside tumor T-cells." (PMID 39337370, 2024).
tapeworm infection (1 paper, 2022). "In addition, the gene expression profile of the pro- and anti-inflammatory cytokines (TNF-α, IL-1β, IL-6 and IL-10) was evaluated by Real-Time PCR to determine the immune response within the CNS to the tapeworm infection." (PMID 35286352, 2022).
testicular tumors (1 paper, 2017). "Bialas and colleagues in 2009 investigated the role of IL-6, IL-10, TNF-α-, TNFR1, and TNFR2 in the processes of normal and abnormal spermatogenesis as well as testicular tumors using Real-Time PCR technique." (PMID 29082371, 2017).
Tetraparesis (1 paper, 2024). Weakness of all four limbs. "Moreover, both anti-IL-6 and IgG isotype–treated aged mice reached a mild tetraparesis and tetraparesis similarly in time." (PMID 38928437, 2024).
tetraplegia (1 paper, 2021). "However, results from this study do not align with this evidence, given that a stronger correlation was observed between IL-6 and neuropathic pain for persons with tetraplegia." (PMID 36188763, 2021).
theileriosis (1 paper, 2019). "The role of IL-6 in immunopathogenesis of theileriosis is unclear." (PMID 30843407, 2019). "The aim was to measure haematological parameters and proinflammatory cytokines (IL-6, TNF-α, IFN-γ) and IgG levels and to determine the correlation of the proinflammatory cytokine levels with haematological parameters during an ovine experimental theileriosis." (PMID 30843407, 2019).
Thiamine deficiency (1 paper, 2023). Thiamine deficiency is a condition that occurs due to not enough thiamine (vitamin B1). "Furthermore, thiamine deficiency highly increases inflammatory cytokines such as IL-1, IL-6, and TNF-α." (PMID 37427326, 2023).
thoracic cancer (1 paper, 2022). A primary or metastatic malignant neoplasm affecting the tissues of the thorax. "It has already been reported that Cisplatin increases cytokines and growth factors as IL6, IL8 and FGF2 in solid tumors, including thoracic cancers." (PMID 35880098, 2022).
thymic lymphomas (1 paper, 2015). "Thus, it is possible that TGF-β and IL-6 in serum may be involved in the DCs dysfunction in thymic lymphoma." (PMID 25923834, 2015). "To identify the serum factors contributing to these effects, we measured the immunosuppressive cytokines level in serum from mice with radiation-induced thymic lymphomas, and found that the level of TGF-β and IL-6 were higher than in the control." (PMID 25923834, 2015).
thymus (1 paper, 2024). "The other theories of thymus atrophy indicate the involvement of other factors, such as the synthesis of IL-6 and TNF-α and leptin deficiency." (PMID 39599720, 2024).
thyroid storm (1 paper, 2024). "Inflammatory markers, such as CRP and IL-6, have become a focal point, with elevated levels associated with the underlying inflammatory processes in the thyroid storm." (PMID 38552097, 2024). "Inflammatory Markers, such as C-reactive protein (CRP) and interleukin-6 (IL-6), have emerged in recent research as potential contributors to the diagnostic landscape, as their elevation can be indicative of thyroid storm." (PMID 38552097, 2024). "Recent research exploring the utility of inflammatory markers like CRP and IL-6 in diagnosing thyroid storm sparks debate." (PMID 38552097, 2024).
tick-borne diseases (1 paper, 2021). "In recent years, many publications have suggested that IL-6 is useful as an inflammatory marker for various diseases and likely to increase the acute-phase response during inflammation, especially in tick-borne diseases." (PMID 34840450, 2021).
tinea capitis (1 paper, 2016). "The IL6-174 G>C SNP was genotyped in 1269 individuals formerly irradiated for tinea capitis." (PMID 27662210, 2016).
tracheobronchitis (1 paper, 2022). Inflammation of the tracheobronchial tree. "In addition, organic acid component, as the main active ingredient of pugongying, can improve acute tracheobronchitis by downregulating the protein expression levels of TNF-α and IL-6." (PMID 36278166, 2022).
Tracheomalacia (1 paper, 2019). "The expressions of IL-5, IL-6, and IL-10 in BALF of AVP were significantly higher than those of MPP and tracheomalacia patients (p-value: 0.016, <0.001, <0.001, respectively)." (PMID 31316955, 2019). "The expression levels of IL-6, IL-8, and IL-10 were significantly higher in inpatients with AVP compared to children hospitalized with tracheomalacia or MPP." (PMID 31316955, 2019).
transient arthritis (1 paper, 2023). Arthritis that is not permanent. "Among the six monocyte-related cytokines/chemokines which peaked at day 1 post-immunization, five (MCP-1, IL-1Ra, TNF-α, IL-10 and IL-6) defined a signature that was vaccine dose-dependent and correlated with viremia, biological outcomes and adverse events, including transient arthritis." (PMID 38235127, 2023).
transitional cell neoplasm (1 paper, 2008). "Indeed, BCG induced IL-6 expression by human transitional cell neoplasms requires NF-kappaB and AP-1." (PMID 18267009, 2008).
traumatic stress disorder (1 paper, 2025). "We were unable to show changes in the circulating concentrations of IL10, IL6, and TNFα after stress, as previously reported in health volunteers, and for IL6 in patients with post‐traumatic stress disorder undergoing stress." (PMID 40584280, 2025).
Trichinella spiralis infection (1 paper, 2018). "Trichinella spiralis infection markedly enhanced the levels of proinflammatory cytokines (TNF-α, IL-6, IL-17, and ICAM-1, P < 0.01) but remarkably reduced the level of anti-inflammatory cytokine (IL-10) in colon, compared with control group (P < 0.01)." (PMID 29662452, 2018).
trichotillomania (1 paper, 2017). A disorder characterized by repetitive pulling out of one's hair resulting in noticeable hair loss; the individual experiences a rising subjective sense of tension before pulling out the hair and a sense of gratification or relief when pulling out the hair. "The current study examined a range of salivary inflammatory markers (IL-1β, IL-6, IL-8, and TNF-α) in a sample of patients with trichotillomania, and whether inflammation related to symptom severity and other clinical measures." (PMID 29920483, 2017).
Tricuspid regurgitation (1 paper, 2009). Failure of the tricuspid valve to close sufficiently upon contraction of the right ventricle, causing blood to regurgitate (flow backward) into the right atrium. "Higher interleukin-6 concentration was a direct predictor of increasing tricuspid regurgitation velocity (beta = 0.22) and it also was associated with higher VEGF and PDGF-BB concentrations." (PMID 19956689, 2009). "According to this analysis, higher hemolytic component was a direct predictor of increasing tricuspid regurgitation velocity (beta = 0.38) and it also was associated with lower hemoglobin concentration and higher interleukin-6 concentration." (PMID 19956689, 2009). "Greater values for PDGF-BB (P = 0.009), interleukin-6 (P = 0.019) and the hemolytic component (P = 0.026) were each independently associated with increased odds of elevated tricuspid regurgitation velocity while higher VEGF concentrations were associated with decreased odds (P = 0.005)." (PMID 19956689, 2009). "Interleukin 6, interleukin 8, interferon-γ, tumor necrosis factor-α, RANTES and PDGF-BB correlated positively with tricuspid regurgitation velocity." (PMID 19956689, 2009). "Plasma VEGF concentration had significant positive relationships with PDGF-BB and interleukin-6 but not with tricuspid regurgitation velocity in bivariate analyses." (PMID 19956689, 2009). "Hemoglobin oxygen saturation did not have a significant independent association with tricuspid regurgitation velocity after adjustment for the hemolytic component, VEGF, PDGF and interleukin-6 in the logistic regression model." (PMID 19956689, 2009).
type 2 thrombocytopenia (1 paper, 2013). "In several cell lines, PaCS development follows cell differentiation/activation by trophic factors and cytokines, such as GM-CSF and IL-4 for DCs, IL-2 and IL-15 for NK cells, or thrombopoietin, IL-6 and IL-11 for megakaryocytes in type 2 thrombocytopenia." (PMID 24358206, 2013).
type IV hypersensitivity reaction (1 paper, 2024). "Metal implants have the potential to trigger a type IV hypersensitivity reaction, where macrophage activation, induced by implant debris, leads to the release of interleukin (IL)-1b, the tumor necrosis factor, IL-6, and IL-8." (PMID 38592148, 2024).
undifferentiated ovarian carcinoma (1 paper, 2000). An aggressive carcinoma arising from the ovary. "IL-6 activity was higher in serous/mucinous than in endometrioid and undifferentiated ovarian carcinoma PCF (P = 0.05)." (PMID 10682675, 2000).
undifferentiated pleomorphic sarcoma (1 paper, 2024). An undifferentiated soft tissue sarcoma characterized by the presence of a pleomorphic malignant cellular infiltrate. "Although we reported the significance of IL-6 in undifferentiated pleomorphic sarcoma (UPS), the critical cytokines in OS remain inadequately understood." (PMID 38302407, 2024).
ureteral stone (1 paper, 2024). "In these procedures involving kidney or ureteral stone manipulation, IL-6 serves as an inflammation marker." (PMID 38327930, 2024).
uterine carcinosarcoma (1 paper, 2022). A usually aggressive malignant neoplasm arising from the uterine corpus and less often the cervix. "FOXQ1 also activated the following pathways in uterine carcinosarcoma: the androgen response pathway, IL6/JAK/STAT3 signaling pathway, interferon–alpha response pathway, adipogenesis pathway, and allograft rejection pathway." (PMID 36118871, 2022).
vascular malformation (1 paper, 2021). A non-neoplastic disorder that is the result of defects of vascular morphogenesis. "Together, these findings indicate an important role for IL6 in the pathophysiology of vascular malformations, warranting further study." (PMID 34479577, 2021). "In recent years, there has been increased focus on the role of IL6 in the pathophysiology of vascular malformations." (PMID 34479577, 2021).
Veno-occlusive disease (1 paper, 2015). "Veno-occlusive disease was accompanied by a significant increase in levels of IL-6, IL-8 and TNF-α.Graft-versus-Host disease was associated with a significant increase of IL-10, sIL-2R, IL-6 and TNF-α, depending on the respective stage or grade." (PMID 26315105, 2015).
venous insufficiency (1 paper, 2018). Impaired venous blood flow or venous return (venous stasis), usually caused by inadequate venous valves. "Elevated levels of D-dimer, interleukin-6 (IL-6), interleukin-8 (IL-8), and C-reactive protein (CRP) levels were found within varicose vein blood in patients with venous insufficiency, compared with upper extremity blood samples." (PMID 29641492, 2018).
vitamin D (1 paper, 2014). "Upon A. fumigatus exposure, vitamin D deficiency led to enhanced and sustained expression of TNF-α, IL-1β, IL-6, CXCL1 and CCL3 both in vivo and in vitro." (PMID 24926881, 2014).
VRSA infection (1 paper, 2023). "In accordance, VRSA infection provoked upregulated relative mRNA expression levels of pro-inflammatory genes (IL-1β, TNF-α, and IL-6) and apoptosis-associated genes (caspase-3, caspase-9, and Bax)." (PMID 38282617, 2023).
vulvar cancer (1 paper, 2022). "Cervical and vulvar cancer cells can inhibit the maturation and function of DCs through the secretion of factors such as IL-6, prostaglandin E2 (PGE2), receptor activator of NF-KB ligand (RANKL), and indoleamine 2,3-dioxygenase (IDO)." (PMID 35207374, 2022). "Indeed, in vitro stimulation of tumor-containing TDLN single-cell suspensions from patients with either cervical or vulvar cancer with different TLR agonists failed to overcome apparent T-cell anergy but instead increased the release of immune-suppressive cytokines, such as IL-6 and IL-10." (PMID 35207374, 2022).
Weil's disease (1 paper, 2024). A jauncice caused by severe leptospirosis. "Patients with Weil’s disease may present with a cytokine storm characterized by high levels of IL-6, IL-10, and tumor necrosis factor-alpha (TNF-α)." (PMID 38398036, 2024).
white matter hyperintensities (1 paper, 2023). "Both higher white matter hyperintensities (WMH) and higher BMI contributed to increased deep-to-periventricular WMH ratio through elevated IL-6 rather than CRP, although CRP was in the similar tendency." (PMID 36334250, 2023).
X-linked agammaglobulinemia (1 paper, 2012). X-linked agammaglobulinemia (XLA) is a clinically variable form of isolated agammaglobulinemia, an inherited immunodeficiency disorder (see this term), and is characterized in affected males by recurrent bacterial infections during infancy. "Impaired TLR-8-mediated IL-6 and TNF-α production in antigen-presenting cells from patients with X-linked agammaglobulinemia was observed." (PMID 22547990, 2012).
X-linked lymphoproliferative disease (1 paper, 2022). X-linked lymphoproliferative disease is a hereditary immunodeficiency characterized, in the majority of cases, by an inadequate immune response to infection with the Epstein-Barr virus (EBV). "The IL-6, IL-10, and IFN-γ levels and the ratios of IL-10 to IFN-γ were different among EBV-HLH, other infection-associated HLH, malignancy-associated HLH, familial HLH, and X-linked lymphoproliferative disease." (PMID 35296096, 2022).
xanthomatosis (1 paper, 2014). A condition marked by the development of widespread xanthomas, yellow tumor-like structures filled with lipid deposits. "Interestingly, we observed that both forms of normolipidaemic xanthomatosis were associated with a common inflammatory pattern characterized by increased CRP and plasma levels of classical pro-inflammatory cytokines (IL-6 and TNFα)." (PMID 24428816, 2014).
yang deficiency (1 paper, 2025). Yang deficiency is a concept from traditional Chinese medicine. "The results of this study demonstrated that the CLHT method, when used in combination with inhaled medications, significantly reduced serum IL-6 and -8 levels in patients with Yang deficiency with water overflowing type COPD compared with controls." (PMID 41450998, 2025).
Zellweger syndrome (1 paper, 2020). "To test whether peroxisomal dysfunction in patients with Zellweger syndrome also induces the production of proinflammatory cytokines, we measured the expression of IL-6 and the phosphorylation of JNK in PEX1-G843D-PTS1 cell line." (PMID 32523050, 2020).